KIF7 (kinesin family member 7)
Diseases named in the same sentence as KIF7 in open-access papers (continued):
Sharing a sentence is not in itself a finding about the gene and the disease.
epilepsy (2 papers, 2024 to 2025). A brain disorder characterized by episodes of abnormally increased neuronal discharge resulting in transient episodes of sensory or motor neurological dysfunction, or psychic dysfunction. "Patients carrying mutations in the KIF7 gene are classified as ciliopathic patients and display DD, ID, and epilepsy." (PMID 40956303, 2025). "Our results show developmental defects leading to permanently displaced neurons, abnormal formation of cortical layers, and defective cortical circuits that could be responsible for epilepsy and/or intellectual disability in patients carrying KIF7 mutation." (PMID 40956303, 2025).
benign prostatic hyperplasia (1 paper, 2017). A non-cancerous nodular enlargement of the prostate gland. "Our results showed that KIF7 was significantly downregulated in PCa, compared with normal, benign prostatic hyperplasia and prostate intraepithelial neoplasia tissues, partially through promoter hypermethylation." (PMID 28903364, 2017).
choriocarcinoma (1 paper, 2014). An aggressive malignant tumor arising from trophoblastic cells. "Downregulation of Gli1, Gli2, Gli3 and Kif7 was demonstrated in clinical samples of choriocarcinoma and hydatidiform moles as well as choriocarcinoma cell lines when compared with normal placentas." (PMID 25265279, 2014). "Ectopic expression of Kif7 in two choriocarcinoma cell lines JAR and JEG-3 led to a decrease in cell growth and increase in apoptosis demonstrated by MTT and TUNEL assays, respectively." (PMID 25265279, 2014).
cleft palate (1 paper, 2012). Cleft palate is a fissure type embryopathy that affects the soft and hard palate to varying degrees. "Patients with mutation in the KIF7 gene in the context of an acrocallosal or fetal hydrolethalus phenotype were frequently found to have polydactyly and occasionally cleft palate, but not mesoaxial polydactyly, tongue hamartoma, additional frenula, or hypothalamic hamartoma." (PMID 22236771, 2012).
colon cancer (1 paper, 2022). "Surprisingly, we also found KIF7 as a high-risk gene in colon cancer." (PMID 35991564, 2022).
gastric cancer (1 paper, 2017). A primary or metastatic malignant neoplasm involving the stomach. "Further, down-regulation of KIF7 is not only restricted to PCa but also present in other cancer types such as breast, renal, melanoma, lung, colorectal, oral, bladder urothelial and gastric cancers as well as vulvar intraepithelial neoplasia." (PMID 28903364, 2017).
gestational trophoblastic disease (1 paper, 2014). "Taken together, Kif7 may contribute to pathogenesis of gestational trophoblastic disease through enhancing survival and promoting dissemination of trophoblasts." (PMID 25265279, 2014).
glioma (1 paper, 2024). A benign or malignant brain and spinal cord tumor that arises from glial cells (astrocytes, oligodendrocytes, ependymal cells). "In the most recent study of the anti-glioma effect, HG inhibited the proliferation of the U87 human glioma cell line in a concentration-dependent manner by decreasing the expression of kinesin family member 7 (KIF7), which is an important component of the hedgehog signaling pathway." (PMID 38962311, 2024).
hydatidiform mole (1 paper, 2014). A gestational trophoblastic disorder characterized by marked enlargement of the chorionic villi, hyperplasia of the villous trophoblastic cells and hydropic changes. "Our real time PCR experiments demonstrated reduced Kif7 expression in both clinical samples and cell lines of CCA when compared with normal placental trophoblasts or hydatidiform moles." (PMID 25265279, 2014).
hydrocephaly (1 paper, 2024). "Hydrolethalus syndrome manifests with hydrocephaly, micrognathia, postaxial polydactyly of the upper limbs, and pre- or postaxial polydactyly of the lower limbs and hallux duplication and is associated with a homozygous deletion in the KIF7 coiled-coil domain." (PMID 38646780, 2024).
microcephaly (1 paper, 2020). A congenital or acquired developmental disorder in which the circumference of the head is smaller than normal for the person's age and sex. "We observed one single m6A site near the stop codon in 7 microcephaly-related E-SMRs, including Brca2, Cep152, Ddx11, Nde1, Kif14, Stil and Cdk5rap2, 3 polymicrogyria-related E-SMRs (Eomes/Tbr2, Pax6 and Foxp2), and 3 megalencephaly-related E-SMRs (Gli3, Ccnd2 and Kif7)." (PMID 32992647, 2020).
Micrognathia (1 paper, 2016). Developmental hypoplasia of the mandible. "In addition, two foetuses with a homozygous deletion in the KIF7 gene showed a phenotype of hydrocephaly, cleft palate and micrognathia, which was similar to the proband’s phenotype." (PMID 27218255, 2016).
Miscarriage (1 paper, 2025). A pregnancy that ends at a stage in which the fetus is incapable of surviving on its own, defined as the spontaneous loss of a fetus before the 22th week of pregnancy. "Additionally, the causal relationship between KIF7 gene dysfunction and recurrent miscarriage remains to be experimentally verified in subsequent research." (PMID 40927360, 2025). "Furthermore, OGM accurately identified the chromosomal breakpoint in the carrier from family 1 and discovered a novel translocation variant of the KIF7 gene associated with miscarriage in this region, as verified by Sanger sequencing." (PMID 40927360, 2025).
multiple epiphyseal dysplasia (1 paper, 2012). Multiple epiphyseal dysplasias (MED/EDMs) are characterized by epiphyseal anomalies causing joint pain early in life, recurrent osteochondritis and early arthrosis. "We report the first missense homozygous disease-causing mutation in KIF7 and expand the clinical spectrum associated with mutations in this gene to include multiple epiphyseal dysplasia." (PMID 22587682, 2012).
prostate carcinoma (1 paper, 2017). A carcinoma that arises from epithelial cells of the prostate gland. "This study investigated kinesin family member 7 (KIF7) expression and function in prostate cancer (PCa)." (PMID 28903364, 2017).
prostate tumor (1 paper, 2017). "In addition, we also confirmed that KIF7-MD could not inhibit prostate tumor growth in PC3-derived xenografts in vivo." (PMID 28903364, 2017).
Retinal dystrophy (1 paper, 2024). Retinal dystrophy is an abnormality of the retina associated with a hereditary process. "We report on a patient with a pathogenic heterozygous mutation on the KIF7 gene who has retinal dystrophy." (PMID 39036105, 2024). "Further research is necessary to better understand the role of the KIF7 gene in retinal dystrophies." (PMID 39036105, 2024). "Further studies are warranted to better understand the role of the KIF7 gene in retinal dystrophies." (PMID 39036105, 2024).
spontaneous abortion (1 paper, 2025). Expulsion of the product of FERTILIZATION before completing the term of GESTATION and without deliberate interference. "To further validate the clinical relevance of KIF7 variations in recurrent spontaneous abortion (RSA), we plan to investigate KIF7 expression levels and related molecular pathological features in an expanded cohort of RSA patients and abortus tissues." (PMID 40927360, 2025).
cancer (12 papers, 2012 to 2024). A tumor composed of atypical neoplastic, often pleomorphic cells that invade other tissues. "KIF7 is a member of the kinesin family that plays a significant role in cancer proliferation." (PMID 34712271, 2021). "Down-regulation of KIF7 is not only restricted to PCa but also present in other cancer types." (PMID 28903364, 2017). "Our discovery that Kif7 is downregulated in CCA may represent a novel mechanism of HH signalling dysregulation in cancer." (PMID 25265279, 2014). "Whether KIF7 plays anti-cancer effect in other cancers needs more convincing evidence." (PMID 28903364, 2017). "However, no direct evidence was provided indicating the role of KIF7 in human cancer development." (PMID 28903364, 2017).
tumor (10 papers, 2012 to 2026). "Aberrations in ciliary function or KIF7 localization can lead to aberrant Hh signaling, promoting tumor aggressiveness and heterogeneity." (PMID 41540036, 2026). "Gli2, the major transcriptional activator of Hh signaling, whose localization and activity can be promoted by KIF7, was reported to function in skin development and tumor suppression." (PMID 34346563, 2021). "Except for KIF7, the remaining genes were differentially expressed between tumor and normal tissues and were statistically significant." (PMID 34346563, 2021). "Our results reveal that KIF7 is a novel tumor suppressor in PCa that acts by suppressing proliferation, migration, invasion and tumorigenicity through LKB1/PTEN/AKT signaling pathway." (PMID 28903364, 2017). "These high-STK38 cells may acquire the capacity to activate Hedgehog signaling through GSK3β and KIF7, thereby promoting the expansion of undifferentiated tumor subpopulations and enhancing tumor plasticity." (PMID 41540036, 2026). "Different domains might have different functions, thus we first investigated whether KIF7-CC possessed a tumor-suppressive function in PCa." (PMID 28903364, 2017). "Notably, in the 22Rv1 xenografts, knockdown of LKB1 attenuated the inhibitory effect of KIF7-CC on tumor growth and restored tumor volumes similar to those found in control xenografts." (PMID 28903364, 2017). "Downregulation of LKB1 abrogated the anti-tumor effects of KIF7-CC in these xenografts." (PMID 28903364, 2017). "As KIF7-CC suppressed prostate carcinogenesis both in vitro and in vivo, we therefore investigated whether KIF7-MD also had anti-tumor functions in PCa." (PMID 28903364, 2017). "It was interesting that Lkb1 also localized in the cilia in mouse embryonic fibroblasts and controlled the length of primary cilia, which had the same effect as Kif7, raising the possibility that LKB1 might play an important role in the tumor suppressive effect of KIF7." (PMID 28903364, 2017). "Likewise, the high BMP4 limits tumor clonogenicity and the influence of WWOX and AP-2 factors on BMP4 expression is similar to that of KIF7." (PMID 35563688, 2022). "We showed for the first time that KIF7-CC but not KIF7-MD acted as a tumor suppressor in PCa." (PMID 28903364, 2017).
skeletal dysplasia (2 papers, 2023 to 2024). Any Mendelian diseases that affects growth and development of the skeleton. "Mutations in KIF5B, KIF7, KIF10, and KIF22 kinesin proteins lead to skeletal dysplasia with various severity of clinical features and overlapping phenotypes." (PMID 38646780, 2024).
infection (1 paper, 2015). The state of being infected such as from the introduction of a foreign agent such as serum, vaccine, antigenic substance or organism. "To better understand the function of KIF7 in the respiratory epithelium, we depleted this protein in MLE15 cells by infection with lentivirus expressing one of two independent Kif7 ShRNA constructs, or scrambled (scram) control virus." (PMID 26439735, 2015).
KIF7 also shares sentences with these, for which no sentence is quoted: epithelial ovarian cancer (2 papers); Al-Gazali-Bakalinova syndrome (1); Ataxia (1); autosomal recessive disease (1); ciliary dyskinesia (1); cognitive deficits (1); cryptorchidism (1); cystic kidney disease (1); developmental delay (1); Down syndrome (1); dysplasia (1); Epiphyseal dysplasia (1); hearing loss (1); hydrolethalus syndrome 2 (1); hypothalamic hamartoma (1); idiopathic scoliosis (1); Joubert syndrome and related disorders (1); kidney disease (1); liver disease (1); Macrocephaly (1); Meckel Gruber syndrome (1); medulloblastoma (1); melanoma (1); metastatic prostate carcinoma (1); Neurodevelopmental delay (1); neurological diseases (1); ocular coloboma (1); ovarian cancer (1); Pfeiffer syndrome (1); porencephaly (1).
A further 11 diseases each share a sentence with KIF7 in 1 paper.